UPK3BL2 (uroplakin 3B like 2)
Tractability: Antibody: UniProt predicts a signal peptide or a membrane-spanning region. PROTAC: ubiquitination databases record sites on it.
Gene: Protein-coding gene on chromosome 7 (102,537,919 to 102,543,696, reverse strand). Ensembl gene ENSG00000284981.
Subcellular location: Membrane
Gene Ontology:
Cellular component: membrane
Genetic constraint (gnomAD): Loss-of-function variants: 0 observed, 1.99 expected, observed/expected ratio (o/e) 0, 90% interval 0 to 1.35. That is too few expected variants to judge how well the gene tolerates losing a copy. Missense variants: 2 observed, 34 expected, observed/expected ratio (o/e) 0.0588, 90% interval 0.023 to 0.19. Synonymous variants: 0 observed, 7.25 expected, observed/expected ratio (o/e) 0, 90% interval 0 to 0.41.
Homologues: Orthologues: macaque UPK3BL2 (93% identical), dog UPK3BL2 (66% identical), mouse Upk3bl (61% identical), rat Upk3bl1 (59% identical), tropical clawed frog upk3b (29% identical), zebrafish upk3b (22% identical). Paralogues in human: UPK3BL1 (100% identical), UPK3B (38% identical), UPK3A (22% identical).